RYR1 (ryanodine receptor 1)
Diseases named in the same sentence as RYR1 in open-access papers (continued):
Sharing a sentence is not in itself a finding about the gene and the disease.
cancer (73 papers, 2008 to 2025). A tumor composed of atypical neoplastic, often pleomorphic cells that invade other tissues. "With regard to disease category, seven individuals had a P/LP variant in five genes associated with inherited cardiac disease, three individuals had variants in cancer‐related genes, and two individuals had P/LP variants in RYR1 (miscellaneous phenotypes)." (PMID 40970488, 2025). "The effects of specific RYR1 variants have also been explored in several knock-in mouse models that reproduce malignant hyperthermia (MH)." (PMID 41301517, 2025). "Multiple Ca2+-handling proteins, including CACNA1D, CACNA2D1, TRPV4, TRPV1, TRPM4, MCU, and RyR1, exhibit cancer-associated overexpression or functional changes, correlating with poor prognosis and aggressive disease features." (PMID 41226294, 2025). "A deleterious RYR1 g.1843T allele to cause malignant hyperthermia and pale, soft, exudative meat was detected in seven heterozygous pigs." (PMID 40723606, 2025). "In cancer-associated bone metastasis in a mouse model, upregulation of Nox4 results in elevated oxidization of skeletal muscle proteins, including RyR1." (PMID 38379095, 2024). "Another relevant issue to be considered is the role of the germline RYR1 variant in the cancer development in this case." (PMID 37510264, 2023). "Five genes, AXIN2, BMP1, CR1, ERBB2, and RYR1, have been recorded of association with birth defects and cancer." (PMID 36384586, 2022). "The difficult interpretation of the pathogenicity of RYR1 variant is reported also by Johnston and colleagues, who focused their attention on RYR1 mutations causing malignant hyperthermia." (PMID 35428369, 2022). "Mutations in the skeletal muscle Ca2+ release channel, the type 1 ryanodine receptor (RYR1), cause malignant hyperthermia susceptibility (MHS) and a life-threatening sensitivity to heat, which is most severe in children." (PMID 33037202, 2020). "The so‐called porcine stress syndrome describes a situation in which pigs with a mutation in the gene encoding the ryanodine receptor 1 (RYR1) respond to stress with malignant hyperthermia and elevated CK levels." (PMID 32097540, 2020). "A particular set of RYR1 alleles renders the channels leaky upon administration of anesthetic agents, leading to a life-threatening condition called malignant hyperthermia." (PMID 31383689, 2019). "The researchers reported that the loss of either glutathione S-transferase omega 1 (GSTO1) or RYR1, reduced the number of cancer stem cells in the primary tumor." (PMID 29443735, 2018). "Recently, signaling events involving interaction of GSTO1 with type 1 ryanodine receptor, RyR1 has been implicated in a signaling pathway that stimulates cancer stem cell enrichment during chemotherapy." (PMID 30487385, 2018). "Causal RYR1 mutations are located outside the hotspot regions or include a malignant hyperthermia causing mutation accompanied by another mutation outside the hotspot regions." (PMID 27855725, 2016). "It is likely that the LMPS combined with the malignant hyperthermia observed in this sibling was associated with mutation in RYR1." (PMID 26932181, 2016). "Second, studies on intact skeletal preparations from normal muscle and muscle susceptible to malignant hyperthermia have shown that withdrawal of extra Ca2+ reduces the sensitivity of RyR1 to caffeine." (PMID 19230144, 2008). "However, in advanced cancers with bone metastasis loss of calstabin from the RyR1 complex together with the post-translational modification of RyR1, results in leaky Ca2+ channels in the sarcoplasmic reticulum." (PMID 36078078, 2022). "RYR1 alteration has been implicated in various types of disease, including cancer." (PMID 27788148, 2016). "Cancer-associated genotypes are dependent on stochastic factors which may account for variable penetrance, while anaesthetic-associated malignant hyperthermia linked to loss-of-function variation in RYR1 is contingent on environmental exposure." (PMID 31974348, 2020).
cancer (continued). "In order to understand the distinct mutational status of each cancer type, we further analyzed the ratio of RYR1, RYR2 and RYR3 mutation types in 30 different cancers." (PMID 36167878, 2022). "Although the number of mutations in RYR2 was significantly higher than RYR1 and RYR3, the ratio of mutation categories in most cancer types was relatively consistent." (PMID 36167878, 2022). "To understand the similarities and differences of cancer mutational status across RYR1, RYR2 and RYR3, we further analyzed the average number of mutations of the three RYR isoforms in different cancer types." (PMID 36167878, 2022). "A single mutation in the skeletal muscle Ca2+ -release channel gene, ryanodine receptor 1 (RYR1), has been reported as causative of malignant hyperthermia." (PMID 34461824, 2021). "As the first RYR1 preclinical model system, studies of R615C pigs led to fundamental discoveries including identification of 4-CmC as a potent RyR1 agonist and identification of RYR1 as a genetic locus for malignant hyperthermia." (PMID 32381029, 2020). "Recently, novel aspect of GSTO1-1 role in cancer progression is shown to be mediated by interaction with type 1 ryanodine receptor, RyR1." (PMID 31861116, 2019). "Mutations in other cancer‐associated genes such as MAGI3, TSC1, PTPN4, RAB3IP, and RYR1 were also identified." (PMID 26432421, 2015). "The somatic mutation rate of RYR1 in CRC is higher than other cancer types, but the enhanced immune function has not been reported." (PMID 36341526, 2023). "Our results demonstrated that RYR1 regulated the expression of key mETC components in USC cells, suggesting that RYR1 may modulate mitochondrial bioenergetics in these cancer cells." (PMID 35953818, 2022). "The Ca2+-dependent stimulation of OXPHOS provide the H+ gradient to maintain the mitochondrial membrane potential for ATP synthesis by F1/F0 ATPase, and inhibition of RYR1 in the cancer cells led to mitochondrial membrane depolarization and reduction in ATP production." (PMID 35953818, 2022). "Three dmCGs with MD > 20% were identified which were associated with HOXA5, further RYR1, known to code for a ryanodine receptor in skeletal muscles and DUSP3, which is implicated in cancer and negatively regulates members of the mitogen-activated protein (MAP) kinase superfamily." (PMID 33547267, 2021). "As mutations of PAK4 and RYR1 tend to co-occur in HGSOC, and the two genes might interact, we hypothesize that caffeine, a cancer drug that targets RYR1, may represent a useful intervention strategy to treat HGSOC patients with PAK4 mutations." (PMID 27788148, 2016). "While RYR1 has previously been linked to autosomal dominant mutations, STAC3, which was formerly associated exclusively with Native American Myopathy/Bailey-Bloch Myopathy, congenital hypotonia, and susceptibility to malignant hyperthermia, is now newly associated with CM-KDS in this study." (PMID 39966651, 2025). "RYR2 may be more expressed than RYR1 and RYR3 in tissues such as lung and gastrointestinal organs and tract, where the incidence of cancers is high, and this may lead to the identification of more mutations predominantly in RYR2 than RYR1 or RYR3." (PMID 36167878, 2022). "Our driver selection method successfully identified 116 probable novel cancer-causing genes, with 4 discovered in patients having no alterations in any known driver genes: MXRA5, OBSCN, RYR1, and TG." (PMID 33232371, 2020). "Notably, RYR1 and APEX1 are the targets of two FDA-approved cancer drugs (caffeine and lucanthone, respectively)." (PMID 27788148, 2016).
cancer (continued). "Furthermore, a leak of Ca2+ from the type 1 ryanodine receptor (RyR1) channels and a high influx of transmembrane Ca2+ through TRPC channels have been described malignant hyperthermia muscle." (PMID 35547584, 2022).
tumor (22 papers, 2013 to 2025). "Previous studies have reported that high expression of the RYR1 isoform was associated with tumor progression in uterine serous cancer." (PMID 39684225, 2024). "RYR1 suppression in the USC xenograft mouse models dramatically reduced tumor mass and prolonged survival time." (PMID 35953818, 2022). "We also confirm the on-target effect in vivo, female athymic nude mice were first injected with luciferase-labeled ARK1 cells stably expressing RYR1 shRNAs or control shRNAs intraperitoneally to establish tumor." (PMID 35953818, 2022). "RYR1 suppression can be applied therapeutically for the treatment USC, which is supported by the test-of-concept experiment showing that the RYR1 antagonist dantrolene could effectively reduce USC tumor burden and progression in the xenograft mouse models." (PMID 35953818, 2022). "In addition, we determined that these immune competent mice display the same biochemical signature of RyR1 oxidation leading to skeletal muscle SR Ca2+ leak as immunodeficient mice with human tumor cells." (PMID 29312148, 2017). "Given the central role of RyRs in calcium signaling, and the involvement of these proteins in pathways relevant to tumor progression, we speculate that the expression and activity of RyRs such as RYR1 may have an effect on the response of HNC patients to treatments." (PMID 39684225, 2024). "The four candidate genes (CACNA1S, ATP2A1, RYR1, and MYLK3) of Ca2+ signaling have special functions in tumor progression." (PMID 35509066, 2022). "Indeed, skeletal muscle RyR1 channels from mice with 4T1 OCIB were oxidized, nitrosylated, and depleted of calstabin compared to non-tumor control mice." (PMID 29312148, 2017). "It works together with the ER channel proteins, ATP2A1 and RYR1; regulates the intracellular calcium concentration, then affects the concentration and function of MLYK3 downstream through the calcium/calmodulin pathway, and finally affects the formation and biological behavior of tumor cells." (PMID 35509066, 2022). "In addition to the 4 mETC genes, we found positive correlations between RYR1 and some other members of NDUF, SDH, COX, and mitochondrial ATPase subfamilies in GEO datasets (GSE24537), suggesting that these mETC genes may play a role in mediating the tumor-promoting effect of RYR1 in USC." (PMID 35953818, 2022).
skeletal muscle disorder (15 papers, 2012 to 2025). A disease involving the skeletal muscle tissue. "While RYR1 mutations are primarily associated with skeletal muscle disorders, their potential roles in bone disorders require further investigation." (PMID 40462134, 2025). "Pharmacological compounds aimed at correcting abnormal RyR1 function may be of benefit not only in RYR1-related neuromuscular disorders but potentially also a wider range of non-skeletal muscle disorders." (PMID 38326582, 2024). "Given that MH and CCD are autosomal dominantly inherited skeletal muscle disorders and that ablation of one Ryr1 allele is well-tolerated in mice, we hypothesized that preferential ASGS of the mutant RyR1 allele in YS/+ and IT/+ knock-in mice would correct RyR1 function in these mice." (PMID 23152933, 2012).
neuromuscular disease (14 papers, 2013 to 2025). "Awareness of the neuromuscular disease spectrum and potential multisystem involvement in RYR1-related MH and ERM is essential to optimize the diagnostic work-up, improve counselling and and future treatment strategies for patients affected by these conditions." (PMID 34414986, 2021). "Our findings suggest that RYR1-related neuromuscular disease may be a significant cause of FADS/LMPS." (PMID 25476234, 2014). "As a first-tier strategy, we recommend comprehensive gene-panel analysis of all neuromuscular disease-related genes, including those commonly implicated in these diseases (e.g., TTN and RYR1)." (PMID 35628876, 2022). "RYR1-related Myopathies (RYR1-RM) comprise a group of rare neuromuscular diseases (NMDs) occurring in approximately 1/90000 people in the US pediatric population." (PMID 29970108, 2018). "Mutations were found in eight previously known neuromuscular disease genes (CHRND, CHNRG, ECEL1, GBE1, MTM1, MYH3, NEB and RYR1) and four novel neuromuscular disease genes (GPR126, KLHL40, KLHL41 and SPEG)." (PMID 26933539, 2015). "Although pathogenic RyR1-related conditions are considered to be amongst the most common causes of neuromuscular diseases, accurate prevalence data are lacking." (PMID 41392983, 2025). "The family history for neuromuscular diseases was negative in all but one family: here, the index patient was the 42-year-old mother, whose sister carried the same two RYR1 variants in a compound heterozygous state and showed similar muscular symptoms." (PMID 39409197, 2024). "Within this cohort, mutations were found in eight previously known neuromuscular disease genes (CHRND, CHNRG, ECEL1, GBE1, MTM1, MYH3, NEB and RYR1) and four novel neuromuscular disease genes were identified and have been published as separate reports (GPR126, KLHL40, KLHL41 and SPEG)." (PMID 26578207, 2015).
cardiac disease (8 papers, 2009 to 2025). "In contrast to RyR1, the cardiac-disease associated RyR2 mutation, located in the domain interface between the EF hand and S2–S3 loop, did not exhibit a large impact on Ca2+ inhibition of RyR2." (PMID 38159862, 2023). "In favor of this possibility, previous observations suggested that RyRs hypersensitivity to polylysine is associated with cardiac diseases or with modifications of skeletal RyR1 interdomains that trigger malignant hyperthermia." (PMID 20016815, 2009). "The indispensable role of the β8–β9 sequence in channel function is highlighted by its extreme conservation across isoforms and species (including invertebrate RyR), as well as being the target of numerous RyR1/2 mutations associated with skeletomuscular and cardiac disease." (PMID 32077934, 2021). "Although both gain-of-function and loss-of-function RYR1 variants seem to be deleterious, the impact of reduced RYR1 expression (resulting in a moderately reduced overall RYR1 function) in heart disease remains uncertain." (PMID 40060969, 2025).
genetic disease (7 papers, 2014 to 2025). "Here, we demonstrate that perturbed NTD tetramerization is a common molecular mechanism operating in RyR1 and RyR2 genetic disease." (PMID 36311249, 2022). "The introduction of the S2843A mutation offers the potential for a once-in-a-lifetime prime editing treatment applicable to a wide range of patients with leaky RyR1 channels, paving the way for a cost-effective and accessible solution to a complex genetic disorder." (PMID 40243436, 2025).
muscular disorders (5 papers, 2013 to 2025). "Indications of an exaggerated cardiac response despite low peak VO2 in certain RYR1-RM adults are consistent with observations in other muscular disorders." (PMID 40993798, 2025). "Unexpectedly, we identified eight patients with pathogenic variants in genes associated with muscular disorders, including MYH3, MYH7, ALPK3, and RYR1." (PMID 38321032, 2024).
infection (4 papers, 2015 to 2020). The state of being infected such as from the introduction of a foreign agent such as serum, vaccine, antigenic substance or organism. "In addition, individuals with these heat-sensitive RYR1 mutations should take extra precautions to manage other sources of core temperature elevation, such as exercise, stress, infection, and thermogenic drugs." (PMID 33037202, 2020).
metabolic disorders (3 papers, 2020 to 2025). "By establishing a receptor-mediated mechanism of statin myotoxicity, this study opens the door to genotype-informed statin prescribing, rational engineering of “RyR1-silent” lipid-lowering agents, and improved long-term adherence in patients with endocrine and metabolic disorders." (PMID 41430740, 2025).
bone disorder (2 papers, 2023 to 2025). "Our previous finding that skeletal disease-associated RyR1 mutations, R4736Q and R4736W, impaired Ca2+-dependent inhibition, is consistent with the current results." (PMID 38159862, 2023).
neurological diseases (2 papers, 2023 to 2025). "We first became interested in neurological diseases for the simple reason that the identical RyR1 and RyR2 channels present in skeletal and cardiac muscles, respectively, are also expressed in different regions of the brain." (PMID 36647824, 2023).
musculoskeletal disorders (1 paper, 2024). "We observed that MYH7, RYR1, FBN1, TNNT1, MYBPC1, COL1A1, and CHRNB1 were related to musculoskeletal disorders." (PMID 38658807, 2024).
RYR1 also shares sentences with these, for which no sentence is quoted: multiminicore disease (14 papers); glioma (8); cardiac arrhythmia (5); glioblastoma (5); central core myopathy (4); congenital fiber type disproportion (4); rhabdomyolysis-myalgia syndrome (4); congenital myasthenic syndrome (3); dilated cardiomyopathy (3); Hypertension (3); mitochondrial disease (3); neurodegenerative disease (3); brain cancer (2); cervical cancer (2); dysferlinopathy (2); Emery-Dreifuss muscular dystrophy (2); encephalomyopathies (2); genetic muscle diseases (2); hypertrophic cardiomyopathy (2); laminopathies (2); limb-girdle muscular dystrophy (2); Long QT syndrome (2); lung carcinoma (2); melanoma (2); myocardial infarction (2); pancreatic cancer (2); rigid spine syndrome (2); Acidosis (1); acute myeloid leukemia (1); adrenocortical carcinoma (1).
A further 95 diseases each share a sentence with RYR1 in 1 paper.